BRAF (B-Raf proto-oncogene, serine/threonine kinase)
Diseases named in the same sentence as BRAF in open-access papers (continued):
Sharing a sentence is not in itself a finding about the gene and the disease.
melanoma (continued). "Some genes were mostly restricted to certain subtypes; for example, BRAF mutations occurred mostly in melanoma, VHL mutations in kidney clear cell samples, and KEAP1 mutations were found in lung samples." (PMID 34830758, 2021). "Recently, the combination of BRAF inhibitor dabrafenib with MEK inhibitor trametinib was approved by FDA to treat patients harboring BRAF (V600E) mutation in NSCLC (non-small cell lung cancer) or melanoma." (PMID 33841154, 2021). "Prime example of this success is malignant melanoma, where BRAF mutations have led to the generation of effective inhibitors." (PMID 34762341, 2021). "In particular, on the top three predicted drugs, we have found Vemurafenib, an FDA approved drug that can induce cellular apoptosis in melanoma cells that contained BRAF mutation via interfering B-raf/MEK/ERK pathway." (PMID 34260684, 2021). "Targeted therapy for patients whose tumors harbor the BRAFV600 mutation achieves high response rates and OS benefit with the combination BRAF/MEK inhibition and represents the ideal first-line treatment for patients with BRAF-mutated advanced melanoma." (PMID 34571969, 2021). "This establishes a hallmark in the treatment of advanced or metastatic BRAF-melanoma, which is mainly associated with a paradoxical activation of MAPK." (PMID 33672955, 2021). "Regarding neoantigen load, we know that combined BRAF/MEK inhibitor treatment can induce apoptosis in BRAF‐mutated melanoma and, hence, trigger the release of possible tumor‐restricted antigens." (PMID 33449393, 2021). "In conclusion, this analysis confirms the durable and robust antitumor activity and safety of dabrafenib combined with trametinib in Chinese patients with BRAF V600 mutation-positive melanoma, including acral melanoma patients." (PMID 34504796, 2021). "In this study, we demonstrated that treatment with ECCA, a carbazole derivative, significantly blocked the growth of both BRAF-mutated and wild-type melanoma cells." (PMID 34103468, 2021). "BRAF mutated melanomas (nearly half of the total) show response to BRAF and/or MEK inhibitors, allowing the practicing of targeted therapies." (PMID 34683910, 2021). "Melanoma arising in giant congenital nevi harbor the NRAS p.Q61 mutation while the BRAF mutation or fusion is infrequent." (PMID 34440462, 2021). "Since BRAF mutation is frequently observed in melanoma, BRAF inhibitors (BRAFi: dabrafenib, vemurafenib, and encorafenib) are now applied for clinical use, and show drastically higher clinical responses than dacarbazine-based treatments." (PMID 33478111, 2021). "TERT promoter mutations result in several cancer types, including melanoma, and the simultaneous presence with BRAF/NRAS alterations is associated with poor prognosis for the patients." (PMID 33917181, 2021). "This was based on the results of the COMBI-AD Phase III study making it the first oral chemotherapy regimen to prevent cancer relapse for node positive, BRAF-mutated melanoma." (PMID 34771633, 2021). "The clinical experts explained that having a generally good PS even with advanced disease is common in people with unresectable or metastatic BRAF V600 mutation-positive melanoma." (PMID 32291725, 2021). "The company’s economic evaluation compared the cost-effectiveness of Enco + Bini versus Dab + Tram when used to treat advanced (unresectable or metastatic) BRAF V600 mutation-positive melanoma." (PMID 32291725, 2021). "About 50% of advanced melanoma has mutations in position 600 (v600) of the serine/threonine kinase BRAF with some evidence of increased risk of progression in the CNS." (PMID 34207653, 2021). "The most common melanoma genetic driver is mutation of the proto-oncogene serine/threonine kinase BRAF; thus, the inhibition of its MAP kinase pathway by specific inhibitors is a commonly applied therapy." (PMID 33730175, 2021). "Copy number reductions of PTEN were found and as previously been reported in melanoma these were all in lines that also harboured BRAF mutations." (PMID 33549048, 2021).
melanoma (continued). "The use of adjuvant and supplementary therapy targeting BRAF/PI3K/AKT pathways lowers the risk of relapses and is pivotal for patients with BRAF-mutant melanoma." (PMID 37305163, 2021). "To evaluate the usefulness of CTCs as biomarkers of responsiveness to treatment, we next analyzed blood from five patients with BRAF-mutated melanoma (MMbraf1–5), who were treated with BRAF/MEK inhibitors." (PMID 33731038, 2021). "Approximately 50% and 20%–30% of human melanomas have activating mutation in BRAF or NRAS genes, respectively." (PMID 33804655, 2021). "Despite the substantial advances in the treatment of BRAF-mutated melanoma, emergence of resistance remains a major challenge to the lasting success of targeted therapies." (PMID 34440824, 2021). "Although BRAF inhibitors (BRAFi) have greatly improved the prognosis of BRAF-mutated melanoma, drug resistance is a major concern even when they are combined with MEK inhibitors." (PMID 33478111, 2021). "In this study, we report that SIJ1777, a novel GNF-7 derivative, possesses potent anti-cancer effects on melanoma cells harboring BRAF class I/II/III mutations." (PMID 33917428, 2021). "Candidate drivers of localised mutagenesis are also apparent: BRAF mutations associate with mutational enrichments at CTCF binding sites in melanoma, and ARID1A mutations with TSS-specific mutagenesis in pancreatic cancer." (PMID 33941236, 2021). "Cutaneous melanomas are mainly driven by oncogenic mutations in BRAF, NRAS, and NF1, which efficiently activate the MEK/ERK1/2 pathway." (PMID 33916908, 2021). "For instance, BRAF p.V600E mutation is detected in approximately 80% of benign melanocytic nevi, 60% of dysplastic nevi, and only in 40–45% of melanomas, suggesting that the functional effects of the mutation are context-dependent." (PMID 35048058, 2021). "In recent years, V600E mutations in the BRAF gene (v-raf murine sarcoma viral oncogene homolog B) were reported as the most common mutations in melanomas." (PMID 33391380, 2021). "Potential determinants relevant for the optimal screening MRI scan interval are melanoma location and type, metastatic sites, BRAF‐ and NRAS‐mutational status, and LDH‐level at diagnosis." (PMID 34741440, 2021). "Given the frequent occurrence of BRAF mutations in melanoma, BRAF inhibitors, vermurafenib and dabrafenib, have been developed." (PMID 34680938, 2021). "A significant relationship was found between advanced melanoma stages and increased BRAF/NRAS mutation rate (p ≤ 0.001)." (PMID 33723350, 2021). "Understanding the mode of action of Octpep-1 is essential to cultivate its therapeutic potential as a drug candidate against melanoma of BRAF-mutation." (PMID 33672955, 2021). "Another example is using epidermal growth factor receptor (EGFR) inhibitors successfully to treat lung cancers that harbor mutant EGFR, also using BRAF inhibitors to treat the melanomas carrying mutated BRAF." (PMID 34737964, 2021). "Next, we used the patient-derived melanoma cell line A2058 which harbors the catalytically active BRAF-V600E variant to validate the impact of indicated MEKi on reporter dynamics in a different cellular setting." (PMID 33808483, 2021). "BRAF mutations play a critical role in melanoma initiation and progression, and about 25% of all Chinese melanoma patients harbor BRAF mutations." (PMID 34504796, 2021). "The combination of dabrafenib/trametinib has recently been investigated in cancers with BRAF V600E mutations, such as anaplastic thyroid cancer, melanoma, non-small cell lung cancer, and cholangiocarcinoma, and has shown promise in treating these malignancies." (PMID 35106230, 2021). "The signaling via CXCR3 also results in a significant increase inIL-8 expression in BRAF wild type melanomas and these two events have been also associated with melanoma progression." (PMID 35011682, 2021).
melanoma (continued). "A combined approach, consisting of BRAF plus MEK inhibitors, has led to a significant improvement in overall survival (OS) for patients harboring a BRAF V600E/K mutation (35–50% of melanomas)." (PMID 34944843, 2021). "The prevalent mutations in melanoma are in genes encoding for effectors of the Ras pathway such as BRAF or NRAS." (PMID 34830947, 2021). "We constructed a logical model to study, from a dynamical perspective, the differences between melanomas and colorectal cancers that share the same BRAF mutations but exhibit different sensitivities to anti-BRAF treatments." (PMID 33507915, 2021). "These new BRAF-mutated MUG Mel3 cell lines represent a valuable model in melanoma heterogeneity and melanoma pregnancy research." (PMID 34768746, 2021). "In a published “basket” study assessing treatment effects of vemurafenib in BRAF V600-mutated non-melanoma malignancies, two out of 122 cases were STS and one patient achieved a partial response to vemurafenib." (PMID 34356494, 2021). "For example, 9/11 BRAF V600E mutations were in melanoma samples, 9/10 KEAP1 mutations were in lung samples and 5/5 VHL mutations were in clear cell renal cancer samples." (PMID 34830758, 2021). "The frequencies of the various clinical melanoma subtypes and the proportion of patients with melanoma harbouring BRAF mutation differ between Caucasian and Asian patients." (PMID 34115870, 2021). "Approximately 20% of melanoma patients are intrinsically insensitive to targeted therapy even their tumors harbor BRAF mutation." (PMID 34924562, 2021). "Current adjuvant therapy with anti-PD-1 antibodies or targeted therapy in BRAF V600 mutant melanoma has improved 3-year RFS in high-risk stage III melanoma to 43–58%." (PMID 33503861, 2021). "One melanoma carried a BRAF V600E mutation (p.Q61R), and two melanomas carried a NRAS mutation (p.G12D)." (PMID 34065883, 2021). "The best-characterized mutation in melanoma, present in about 40–60% of patients, is in the BRAF proto-oncogene." (PMID 34207514, 2021). "The incidence of BRAF mutation is the highest in melanoma, observed in approximately one half of the cases." (PMID 34575554, 2021). "Combined BRAF-MEK inhibitor (BRAFi/MEKi) therapy was a breakthrough in the treatment of melanoma with BRAFV600-mutations." (PMID 34885166, 2021). "Since BRAF mutations are common in melanoma, BRAF-inhibitors are often used and have a direct effect on tumor regression." (PMID 34572949, 2021). "Particularly, in melanoma cells containing a BRAF mutation, it is thought that glycolysis is enhanced and oxidative metabolism suppressed, promoting resistance to energy stress through ERK activation." (PMID 33430068, 2021). "In melanoma patients, when compared with the real-time PCR (RT-PCR) approach cobas® 4800 BRAF V600 mutation test (Roche, Basel, Switzerland), the Sanger sequencing achieved an overall agreement ranging from 95.2% to 97.7%." (PMID 33801689, 2021). "Mutations in BRAF are one of the most frequent oncogenic molecular events in cancer and in particular have been implicated in malignant melanoma, non-small cell lung cancer, papillary thyroid cancer, and glioma." (PMID 34965294, 2021). "Only one study has mentioned an absence of any correlation between B-cell transcriptomic profile (as TLS signature) and BRAF mutations in melanoma patients treated by neo-adjuvant targeted therapy." (PMID 34276690, 2021). "Other studies using NGS and cancer hotspot panels in paired melanoma samples found the same main driver mutations (BRAF, NRAS, KIT)." (PMID 34680222, 2021). "In this paper, we report for the first time that NECTIN4 is expressed in human melanoma, with an especially higher frequency in BRAF-mutated melanoma." (PMID 33478111, 2021).
melanoma (continued). "The antitumor potential of Ocoxin was studied in foru BRAF-mutated melanoma cell lines, including the murine YUMM-1.7 and the human COLO-800, HT-144, and RPMI-7951." (PMID 33669949, 2021). "The reactivation of ERK seems to be crucial for the resistance to BRAF inhibitors in melanoma cells with BRAF-V600E mutations, and one of the mediators is FGFR3." (PMID 34830951, 2021). "For other cancer types single genomic aberrations have proven to be relevant therapy targets, e.g. BRAF mutations in melanoma or HER2 mutations in breast cancer." (PMID 33712636, 2021). "The combination of BRAF and MEK inhibitors represents the standard of care treatment for patients with metastatic BRAF-mutated melanoma, notwithstanding the high frequency of emergent resistance." (PMID 34136385, 2021). "Specifically, the BRAFV600E mutation, which is the most frequent BRAF mutation in melanoma, stimulates the constitutive activation of the downstream extracellular signal-regulated kinase (ERK)." (PMID 34326399, 2021). "Around 50% of melanoma patients show BRAF mutations, which lead to dysregulated downstream activation of the MEK and ERK pathways." (PMID 34360634, 2021). "The most common mutation, found in around 50% of all melanoma cases, is the BRAF gene mutation, most often the BRAFV600E where valine is substituted with a glutamic acid." (PMID 35127523, 2021). "Several studies also reported that resistance to the K-RAS inhibitor in pancreatic cancer, and BRAF inhibitors in melanoma, is associated with such a shift to oxidative metabolism." (PMID 34073320, 2021). "Specifically, two isomiRs are downregulated (hsa-miR-181a-2-3p|0|+1, hsa-miR-92a-3p|0|+1(+1U)), while the remaining 42 are upregulated in BRAF mutated melanoma patients." (PMID 34698264, 2021). "BRAF-mutated melanoma cells initially respond to BRAF inhibition but rapidly become tolerant when in close contact with stromal cells." (PMID 33807785, 2021). "The first group is the conventional melanoma that shares the histopathological and clinical features of adult melanoma, where 50 – 60% of patients harbor the BRAF V600E mutation and the condition rarely develops before puberty." (PMID 33996584, 2021). "CCND1, which encodes for the Cyclin D1, protein has been shown to be amplified in BRAF-mutated and wild type melanomas." (PMID 34066022, 2021). "Both patients had malignant melanoma with known BRAF V600E mutation and metastasis to the brain as well as additional extracranial metastasis, including to the abdomen and lung." (PMID 33799709, 2021). "In this review, we will discuss potential druggable mutations and the ongoing research of novel individualized treatment approaches targeting non-BRAF mutations in melanomas." (PMID 34831002, 2021). "For example, the BRAF V600E mutation is most commonly seen in human melanoma but is also seen in other cancers; likewise, its canine ortholog V595E is common in transitional cell carcinoma but is also present in different canine cancer types." (PMID 33834049, 2021). "Altogether, this suggests that targeting the RHOJ–PAK axis would be beneficial for melanoma patients with BRAF mutations." (PMID 34503171, 2021). "Materials and methods: Circulating miRNAs were extracted from the serum of 51 BRAF-mutated melanoma patients before the beginning of therapy through miRNeasy Mini Kit (Qiagen)." (PMID 33757523, 2021). "BRAF mutations are present in 66% of malignant melanoma, with the V600E mutant being the most prevalent." (PMID 33746966, 2021). "Despite the conspicuous clinical response of BRAF-mutated melanoma to BRAF inhibitors and the dramatic response rate of immune checkpoint therapies, the prognosis of melanoma patients remains unfavorable, mainly due to the development of drug resistance." (PMID 33800394, 2021). "In spite of the presence of the oncogenic BRAF molecule, nevi are normally associated with an extremely low proliferative activity and rarely progress into melanoma." (PMID 33562468, 2021).
melanoma (continued). "Many studies evaluated the prognostic significance of BRAF mutations but its role in predicting patient outcome in melanoma is controversial." (PMID 33925387, 2021). "Collectively, despite enormous effort, the exact molecular mechanisms why drug resistance evolves in mutated BRAF or NRAS melanomas remain elusive." (PMID 34063141, 2021). "In the present study, we assessed the role of mTORC2/RICTOR in BRAF-mutated melanomas and their resistance to BRAF inhibition." (PMID 34680615, 2021). "Pregnant patients, harbouring a BRAF V600E mutation—the most abundant mutation in melanoma—were described as developing extensive metastatic melanoma during pregnancy or in the first year after birth, with poor survival regardless of therapeutic interventions." (PMID 34768746, 2021). "These tumors were generated independently of BRAF V600E and other melanoma-related mutations in oncogenes and tumor suppressors." (PMID 34575678, 2021). "In BRAF-mutated melanoma, chronic ER stress involving induction of the ISR signaling pathway activates autophagy which contributes chemoresistance." (PMID 34630117, 2021). "NRAS-mutated cutaneous melanoma have an unfavorable prognosis as compared to BRAF mutated or wild-type melanoma." (PMID 34071371, 2021). "ICI or targeted therapy are now the first line treatment in advanced melanoma, depending on the tumor v-raf murine sarcoma viral oncogene homolog B1 (BRAF) mutational status." (PMID 34356899, 2021). "Regarding to melanoma, BRAF V600E mutation deregulates the MAPK signaling pathway that promotes cell proliferation and apoptosis evasion." (PMID 33669949, 2021). "BRAF is the most frequent mutation observed in melanoma patients, with BRAF testing recommended for advanced melanoma patients to permit the selection of the optimal treatment regimen." (PMID 33574842, 2021). "BRAF mutations are associated with poor prognosis in metastatic colorectal cancer, but treatment with drugs such as vemurafenib, which targets BRAF mutations, has demonstrated high efficacy in melanoma patients." (PMID 34884530, 2021). "BRAF codon V600 activating mutations, which affect almost a half of melanoma patients, became a therapeutic target with the development of specific inhibitors—namely BRAF and MEK inhibitors—which are currently used in both adjuvant and metastatic settings." (PMID 34440824, 2021). "Among melanoma patients that received chemotherapy, circulating DNA of mutant BRAF was associated with a significantly worse overall survival compared to wild-type-BRAF patients, corresponding to 13 months and 30.6 months, respectively." (PMID 34209415, 2021). "The BRAF-V600E mutation is present in approximately 50% of melanoma cases and causes constitutive activation of BRAF and the MAPK (ERK) signaling pathway leading to uncontrolled cell proliferation." (PMID 33604667, 2021). "Mutational activation of BRAF is associated with tumor progression and BRAF-mutated melanoma showed higher NECTIN4 expression than melanoma with wild-type BRAF." (PMID 33478111, 2021). "Metabolic rewiring is an established hallmark of cancer, and BRAF mutant melanoma cells exhibit a high level of glycolytic activity (the Warburg effect)." (PMID 34066022, 2021). "For example, BRAF mutations were generally observed in various types of cancer, including colon cancer, thyroid cancer, and melanoma." (PMID 34745259, 2021). "Determining the presence of a BRAF mutation has become a standard of care for advanced melanoma and can help direct treatment with targeted therapies." (PMID 34066966, 2021). "One hundred and five patients with Stage III melanoma and available BRAF mutational status met the inclusion criteria for our study." (PMID 34537078, 2021). "NRAS is mutated in 15–30% of cutaneous melanoma, and patients having NRAS mutations in melanoma are generally older (>55 years), have thicker tumors, and have inferior clinical outcomes in comparison to patients harboring BRAF mutations." (PMID 33807778, 2021).